DNAJB4 (DnaJ heat shock protein family (Hsp40) member B4)
Diseases named in the same sentence as DNAJB4 in open-access papers (continued):
Sharing a sentence is not in itself a finding about the gene and the disease.
lung adenocarcinoma (6 papers, 2012 to 2025). A carcinoma that arises from the lung and is characterized by the presence of malignant glandular epithelial cells. "In a previous study, we screened a series of human lung adenocarcinoma cell lines with varying invasion capabilities by microarray and identified a panel of metastasis-related genes including the human liver DnaJ-like protein (HLJ1, also known as DNAJB4)." (PMID 22529897, 2012). "Analysis through the GEPIA2 online database, we found that the expression of most interaction proteins was not significantly different in lung adenocarcinoma and lung squamous cell carcinoma, and the expression of DNAJB4 was different in LUAD, but not in LUSC." (PMID 40395325, 2025).
colorectal cancer (5 papers, 2016 to 2025). A primary or metastatic malignant neoplasm that affects the colon or rectum. "In colorectal cancer, miR-183 promotes malignant progression by inhibiting DNAJB4, underscoring the significance of miRNA-mediated regulation of tumor suppressor genes in cancer progression." (PMID 40149995, 2025). "Ectopic overexpression of DNAJB4 can dramatically inhibit colorectal cancer cell invasion and metastatic potential." (PMID 36499297, 2022). "DNAJB4 expression is lower in highly metastatic colorectal cancer cells than in poorly metastatic ones." (PMID 36499297, 2022). "DNAJB4 is a potent tumor suppressor of colorectal cancer (CRC)." (PMID 36499297, 2022). "DNAJB4 has also been recognized as a tumor suppressor in colorectal carcinoma." (PMID 36499297, 2022).
melanoma (5 papers, 2019 to 2024). A malignant, usually aggressive tumor composed of atypical, neoplastic melanocytes. "This method successfully identified the differential abundance of HSPs during malignant melanoma metastasis and revealed that DNAJB4 is a suppressor of melanoma metastasis." (PMID 37587463, 2023). "Strikingly, our results showed that a number of heat shock proteins, particularly HSPA1 and DNAJB4, which belong to the HSP70 and HSP40 subfamilies, respectively, displayed markedly elevated expression in M14 melanoma cells upon treatment with the three HSP90 inhibitors." (PMID 31399576, 2019).
respiratory failure (4 papers, 2024). The significant impairment of gas exchange within the lungs resulting in hypoxia, hypercarbia, or both, to the extent that organ tissue perfusion is severely compromised. "Recessive loss-of-function variants in DNAJB4 cause myopathy with early respiratory failure and spinal rigidity, presenting from infancy to adulthood." (PMID 39468638, 2024). "DNAJB4 is an emerging cause of inherited myopathy with respiratory failure and rigid spine syndrome of variable age of onset and severity." (PMID 39468638, 2024). "Homozygous DNAJB4 variants resulting in a myopathy with early respiratory failure with highly variable symptom onset between age 1 and 45 years were only recently reported in four patients." (PMID 38127101, 2024). "It has been shown that loss-of-function variants of DNAJB4 may lead to the accumulation of DNAJB4 client proteins, causing muscle dysfunction and degeneration, leading to early respiratory failure." (PMID 38882679, 2024). "We provide the first independent replication of recessively inherited DNAJB4-related myopathy with respiratory failure, which again emphasizes the scientific value of NGS, regardless of its diagnostic utility." (PMID 38127101, 2024).
hepatocellular carcinoma (3 papers, 2021 to 2024). A malignant tumor that arises from hepatocytes. "Hepatitis B virus (HBV), the leading cause of human hepatocellular carcinoma (HCC), could also promote DNAJB4 transcription in HCC cells by upregulating YY1." (PMID 36499297, 2022).
rigid spine syndrome (2 papers, 2024). "Our findings suggest that DNAJB4 is an emerging cause of myopathy with rigid spine syndrome of variable age of onset and severity." (PMID 39468638, 2024).
Sepsis (2 papers, 2022 to 2023). Sepsis is defined as life-threatening organ dysfunction caused by a dysregulated host response to infection. "It is noteworthy that the serum levels of IFN-γ in anti-IL-12 antibody-injected Dnajb4−/− mice were comparable to those in Dnajb4+/+ mice during sepsis, indicating that HLJ1 enhances IFN-γ expression mainly through IL-12 regulation." (PMID 35983991, 2022). "Dnajb4+/+ and Dnajb4−/− mice showed similar survival rates when LD50 dose of LPS (10 mg/kg) was used, but Dnajb4−/− mice were significantly more resistant to LPS-induced sepsis and exhibited longer survival than Dnajb4+/+ mice when subjected to a higher lethal dose of LPS (20 mg/kg)." (PMID 35983991, 2022). "However, IL-12 neutralization did not significantly improve the survival of Dnajb4−/− mice, indicating that HLJ1 enhanced sepsis death via IL-12 regulation." (PMID 35983991, 2022).
triple-negative breast carcinoma (2 papers, 2023 to 2024). An invasive breast carcinoma which is negative for expression of estrogen receptor (ER), progesterone receptor (PR), and human epidermal growth factor receptor 2 (HER2). "DNAJB4, associated with the severity and poor prognosis of triple-negative breast cancer, promotes apoptosis in these cancer cells by activating the Hippo signaling pathway." (PMID 39513103, 2024).
Alzheimer disease (1 paper, 2021). A progressive, neurodegenerative disease characterized by loss of function and death of nerve cells in several areas of the brain leading to loss of cognitive function such as memory and language. "DNAJB4/HLJ1 is not only implicated in myocardial infarction and Alzheimer’s disease, but also regulates cancer progression." (PMID 34948322, 2021).
bacteremia (1 paper, 2022). "It suggested that severe bacteremia contributed to mortality even in Dnajb4−/− mice before antibiotic administration." (PMID 35983991, 2022).
Cognitive impairment (1 paper, 2024). Abnormal cognition is characterized by deficits in thinking, reasoning, or remembering. "Upregulated Dnajb4 in turn leads to ubiquitination and degradation of the mitochondrial Na + /Ca2+ exchanger NCLX, thereby inducing mitochondrial calcium overload that causes neuronal damage and cognitive impairment in mice." (PMID 39375536, 2024). "Such treatment led to a decrease in binding of Clock to Bmal1 and a downregulation of Bhlhe41 and Dnajb4 expression, resulting in NCLX upregulation and an improvement in mitochondrial calcium overload, hippocampal neuron dysfunction, and cognitive impairment in diabetes." (PMID 39375536, 2024). "Additionally, Dnajb4 upregulation led to NCLX ubiquitination and degradation in hippocampal neurons, which induced mitochondrial calcium overload and impaired mitochondrial function, thereby promoting neuronal apoptosis and cognitive impairment in diabetes." (PMID 39375536, 2024).
distal myopathy (1 paper, 2024). Distal myopathy refers to a group of muscle diseases which share the clinical pattern of predominant weakness and atrophy beginning in the feet and/or hands. "Similar to DNAJB6, DNAJB4 is an HSP40 co-chaperone of HSP70, and a dominant point mutation (p.F90L) in the G/F domain of DNAJB4 was recently found to cause a late-onset distal myopathy with protein aggregate myopathology." (PMID 39501809, 2024).
endotoxemia (1 paper, 2022). "It resulted in lower serum levels of organ dysfunction markers and also IFN-γ in Dnajb4−/− mice comparing with wild-type mice, suggesting the effect of HLJ1 deletion on reducing IFN-γ levels and alleviating organ injury can be found as well during moderate endotoxemia." (PMID 35983991, 2022).
Huntington disease (1 paper, 2020). Huntington disease (HD) is a rare neurodegenerative disorder of the central nervous system characterized by unwanted choreatic movements, behavioral and psychiatric disturbances and dementia. "In particular, the class A cochaperone DNAJA1 as well as the class B cochaperone DNAJB4 are upregulated in patients with AD, PD, and Huntington's disease (HD) compared with age-matched controls." (PMID 32467226, 2020).
liver cancer (1 paper, 2024). An epithelial or non-epithelial malignant neoplasm that arises from the liver. "In this study, we used HLJ1-knockout (Dnajb4–/–) mice and demonstrated that HLJ1 deficiency leads to hepatic gene signatures linked to chemical-induced liver cancer and IL-6/STAT3 signaling." (PMID 39738726, 2024).
ovarian tumors (1 paper, 2023). "According to the HPA, high expression of CAV2, COL11A1, DNAJB4, THY1 and VCAN decreased the 5-year survival for breast, CNS, colon, kidney, lung and ovarian tumors." (PMID 37986165, 2023).
Parkinson disease (1 paper, 2014). A progressive degenerative disorder of the central nervous system characterized by loss of dopamine producing neurons in the substantia nigra and the presence of Lewy bodies in the substantia nigra and locus coeruleus. "Thus heat-shock, cigarette smoke, or chemical treatments with elesclomol or the HSP90-inhibitor geldanamycin, as well as in chronically challenged tissues in Parkinson's disease, type II, DNAJB1 and DNAJB4 were found to be systematically more over-expressed than type I, DNAJA1 and DNAJA2." (PMID 25988148, 2014).
schizophrenia (1 paper, 2016). A major psychotic disorder characterized by abnormalities in the perception or expression of reality. "The schizophrenia specific module, SCH_only_M7, was not correlated with any covariates we tested and contained 76 genes with BAG3, DNAJB1,DNAJB4, HSPAH and HSPA6 the top 5 hub genes in this module." (PMID 27898074, 2016).
tumor (44 papers, 2008 to 2025). "Particularly, high DNAJB4 expression was more common in males and was associated with a smaller tumor size and an earlier cancer stage." (PMID 40149995, 2025). "This suggests a strong association between DNAJB4 expression and these proteins, which may influence tumor behavior through pathways related to angiogenesis, apoptosis, and cell signaling." (PMID 40149995, 2025). "Although CD31 is generally linked to tumor progression, the protective role of DNAJB4 remains unclear." (PMID 40149995, 2025). "There were significant differences in DNAJB4 expression according to sex, tumor size, and cancer stage." (PMID 40149995, 2025). "Sex distribution, tumor size, and cancer stage were significantly different between the low (n = 61) and high (n = 127) DNAJB4 expression groups." (PMID 40149995, 2025). "In non-muscle-invasive bladder cancer (NMIBC), HERV-H-derived miR-4454 is upregulated, which inhibits the expression of the tumor suppressor genes DNAJB4 and SASH1, thereby promoting NMIBC progression." (PMID 40149995, 2025). "Although CD31 typically indicates tumor progression, the protective role of DNAJB4 appears related to caspase-3-mediated apoptosis, as shown in the late-stage subgroup analysis." (PMID 40149995, 2025). "In non-small cell lung cancer (NSCLC), circ_0009043 is upregulated and suppresses DNAJB4 expression by sequestering miR-148a-3p, thereby promoting tumor progression." (PMID 40149995, 2025). "The complex interplay between proliferation and apoptosis in tumors suggests that further research is needed to clarify the impact of DNAJB4 on tumor behavior." (PMID 40149995, 2025). "Collectively, our results and those of previous studies support that high DNAJB4 expression promotes increased caspase-3 levels, thereby enhancing tumor cell apoptosis and providing a protective effect." (PMID 40149995, 2025). "The results showed Dnajb4–/– mice exhibited significantly higher macroscopic tumor burdens compared to Dnajb4+/+ mice." (PMID 39738726, 2024). "Phosphorylated 5‘ AMP-activated protein kinase (pAMPK) and DNAJB4 play roles in cellular stress responses, where pAMPK can have both tumor-suppressive and tumor-promoting effects." (PMID 39597836, 2024). "Tumor multiplicity, volume, and relative liver weight were also significantly elevated in Dnajb4–/– mice." (PMID 39738726, 2024). "To clarify the role of HLJ1 in the liver microenvironment and characterize its spatial expression during tumor progression, we performed immunohistochemical staining on serial liver sections from Dnajb4+/+ mice." (PMID 39738726, 2024). "Consistent with the primary model, Dnajb4–/– mice exhibited a 100% incidence rate, greater macroscopic tumor burden, and higher multiplicity (number of tumors) than Dnajb4+/+ mice." (PMID 39738726, 2024). "Microscopically, the size of LLC and B16F1 tumor lesions in the liver was significantly larger in Dnajb4–/– mice than in Dnajb4+/+ mice." (PMID 39738726, 2024). "In summary, DNAJB4 is regulated by miR-183-5p, which affects the activation of the Hippo signaling and thus alters the tumor immune microenvironment and ultimately regulates the biological behavior of MCF-7 cells." (PMID 37548821, 2023). "The high expression of DNAJB4 is related to high levels of stromal cell infiltration and lower tumor cell purity in BRAC." (PMID 37548821, 2023). "DnaJ heat shock protein family (Hsp40) member B4 (DNAJB4), also called HLJ1, is another well-known tumor suppressor gene that inhibits the invasion, migration, and proliferation of cancer cells." (PMID 37510314, 2023). "To validate the role of DNAJB4 in vivo, we established a xenograft tumor model with the mouse 4T1 cell in Balb/c mice." (PMID 37548821, 2023). "Hsp40 family members such as Tid I (class DnaJ A3) and HLJ1 (class DnaJB4) have been reported to be involved in the regulation of tumor development." (PMID 35570564, 2022).
tumor (continued). "Conversely, miR-148a-3p inhibition resulted in the suppression of NSCLC cell apoptosis and the enhancement of tumor cell growth, while the downregulation of DNAJB4 reversed these changes." (PMID 35974419, 2022). "In these cases, while NR2F1 is associated with cancer cell dormancy, DNAJB4 acts as a suppressor for cancer cell metastasis and STON2 negatively modulates tumor stemness and tumorigenesis." (PMID 34722496, 2021). "For example, HSP90AB1, an oncogene, was upregulated in 8 cancer types, while DNAJB4, a tumor suppressor, was down-regulated in 12 cancer types." (PMID 33225964, 2020). "HLJ1 (DNAJB4), a member of subclass B, is tumor suppressor in nature, but inversely associated with tumor invasion." (PMID 28914774, 2017). "DNAJB4 (DnaJ heat shock protein family member B4) is a chaperone with a strong tumor suppressor effect in CRC whose down-regulation has been associated with patient outcome." (PMID 27662660, 2016). "This suggests that DNAJB4 may exert its protective effect by enhancing caspase-3-mediated apoptosis, despite the complexity of tumor proliferation and apoptosis pathways." (PMID 40149995, 2025). "Furthermore, HERV-H-derived miR-4454 promotes the progression of NMIBC by downregulating tumor suppressor genes, such as DNAJB4, reinforcing the role of DNAJB4 as a tumor suppressor." (PMID 40149995, 2025). "However, tumor tissues in Dnajb4–/– mice showed enhanced cell proliferative activity, as indicated by increased PCNA staining." (PMID 39738726, 2024). "Above results suggest, DNAJB4 overexpression inhibits xenograft tumor growth." (PMID 37548821, 2023). "Similarly, in vivo experiments verified that DNAJB4 influenced tumor growth through Hippo regulation of the tumor immune microenvironment." (PMID 37548821, 2023). "Meanwhile, overexpression of DNAJB4 in MDA-MB-231 cell line promoted tumor cell apoptosis in vitro." (PMID 37012515, 2023). "Studies have shown that DNAJB4 can interact with some intracellular proteins and participate in the regulation of tumor occurrence and development through molecular signaling pathways and other factors, but its mechanisms are still unknown." (PMID 37012515, 2023). "However, recent reports of the involvement of some Hsp40 members of distinct classes such as hTid I (class 3HDNAJA3) and HLJ1 (class DNAJB4) in modulation of tumor growth are emerging." (PMID 18328103, 2008). "DNAJB4 may influence tumor biology, angiogenesis, and tumor progression." (PMID 40149995, 2025). "Above results suggests that DNAJB4 may act as a tumor suppressor in MCF-7 cells." (PMID 37548821, 2023). "Thus, miR-183-5p could directly regulate DNAJB4 expression, thereby affecting Hippo signaling and changing tumor growth." (PMID 37548821, 2023). "We hypothesized that DNAJB4 therapy may also influence tumor immunity." (PMID 37548821, 2023). "In addition, accumulating studies have suggested that DNAJB4 is involved in various cancers as a tumor suppressor that could inhibit cancer cell proliferation, invasion, and metastasis." (PMID 36499297, 2022). "Furthermore, we used regression coefficients for HERPUD1, MAP3K8, GAPDH, and DNAJB4 to construct risk score models as follows: risk score = −0.197∗MAP3K8 −0.261∗HERPUD1+ 0.185∗GAPDH+ 0.191∗DNAJB4 and calculated the risk score for each LUAD tumor sample." (PMID 34295900, 2021). "The specific high expression of DNAJB4 in LUAD further supports its potential as a subtype marker, and its spatial and temporal distribution in the tumour microenvironment can be resolved in the future using single-cell spatial transcriptomic techniques." (PMID 40395325, 2025). "Experimental manipulation through DNAJB4 knockdown exhibited a pro-tumorigenic effect by inhibiting TNBC cell apoptosis and promoting tumor growth, both in vitro and in vivo." (PMID 38473804, 2024).